CDK6 (cyclin dependent kinase 6)
Diseases named in the same sentence as CDK6 in open-access papers (continued):
Sharing a sentence is not in itself a finding about the gene and the disease.
glioma (continued). "MicroRNA-675, encoded in the first exon of H19, regulates cell proliferation and migration through CDK6, a pivotal regulator in cell cycle, in glioma and predicting a poor prognosis of glioma patients." (PMID 27063004, 2016). "Reduced levels of miR-34a were also observed in human gliomas, which correlated with increased expression of the target oncogenes c-Met, Notch-1/2 and cyclin-dependent kinase 6 (CDK6) in glioma and stem cells." (PMID 24275848, 2013). "Further studies will be required to determine the precise mechanism by which over-expression of miR-495 decreases CDK6 expression and inhibits glioma cell proliferation." (PMID 23594394, 2013). "Analyses of clinical specimens from GBM patients identified that CDK6 is significantly expressed in gliomas." (PMID 23594394, 2013). "The aim of this study was to assess the possible prognostic value of cyclin-dependent kinase 6 (CDK6) and the effects of microRNA-495 (miR-495) manipulation on CDK6 expression and cell survival in glioma cells." (PMID 23594394, 2013). "Specifically, miR-125b regulates the proliferation of U251 glioma stem cells through the cell cycle-regulated proteins CDK6 and CDC25A." (PMID 23594394, 2013). "Our previous study showed that miR-125b is critical for the suppression of human U251 glioma stem cell proliferation through regulating the cell cycle proteins CDK6 and CDC25A." (PMID 23554660, 2010). "Interestingly, in a study of VER in glioma, it also caused G0/G1 phase cell cycle arrest in three glioma cell lines by preventing the development of the cyclin D-CDK4/CDK6-associated complex." (PMID 41158757, 2026). "Moreover, oncogenic lncRNA H19 was also an inducer of aggressive glioma cell behaviour and targeted miR-200a (which represses oncogenes such as CDK6 and ZEB1)." (PMID 37239035, 2023). "Alternatively, H19 could drive cell growth in glioma cells by sequestering miR-200a, which negatively regulates CDK6 expression." (PMID 37744274, 2023). "Inhibition of CDK6 has also been shown to enhance glioma sensitivity to chemotherapy." (PMID 37298284, 2023). "CDK4 and CDK6, which regulate the cell cycle, played an important role in glioma pathogenesis." (PMID 37273702, 2023). "The cell cycle regulator cyclin-dependent kinase 6 (Cdk6) is also known to be significantly upregulated in glioma cells, and its elevated expression correlates with the grades of glioma malignancy and glioma resistance to chemotherapy." (PMID 35223842, 2022). "In sum, the present research discovered that PCGEM1 was an oncogene in glioma by modulating miR-539-5p/CDK6 pathway, suggesting that PCGEM1 may be a novel therapeutic target." (PMID 33589577, 2021). "Moreover, we noticed that miR-539-5p mimics or CDK6 silencing suppressed the proliferation, migration and invasion of glioma cells in vitro." (PMID 33589577, 2021). "In addition, up-regulation of miR-200a lead to reduction of CDK6 expression and inhibit the proliferation of glioma cells." (PMID 34796112, 2021). "Knockdown of H19 could induce the biological behavior changes of glioma cells by up-regulating miR-200a and down-regulating CDK6/ZEB1." (PMID 34796112, 2021). "Taken together, these results demonstrated that c-Jun enhanced upon HDGF overexpression could promote glioma cell proliferation by inducing the activation of the CCND1/CDK4/CDK6 signaling axis." (PMID 34959221, 2021). "Moreover, our data suggested that enhanced miR-200a expression lead to reduction of CDK6, subsequently inhibiting glioma cell proliferation." (PMID 34796112, 2021). "In consistence with these findings, CDK6 expression was increased in glioma cell lines." (PMID 34796112, 2021). "Moreover, we revealed that CDK6 was regulated by PCGEM1 through inhibiting miR-539-5p in glioma cells." (PMID 33589577, 2021). "In summary, our data revealed that knockdown of H19 may suppress the development of glioma in vivo by up-regulating miR-200a and down-regulating CDK6/ZEB1." (PMID 34796112, 2021).
glioma (continued). "Moreover, the knockdown target genes (MAML2, FAM84B, and CDK6) significantly inhibited the cell proliferation in glioma (p < 0.001)." (PMID 33537074, 2021). "Taken all together, miR-200a could inhibit the proliferation of glioma cells through targeting CDK6." (PMID 34796112, 2021). "NEAT1 and CDK6 could promote tumorigenesis of glioma cells; additionally, miR‐139‐5p restrained the biological functions of glioma cells." (PMID 34178684, 2021). "In the present study, the levels of CDK6 were remarkably elevated in glioma tissues and cells." (PMID 34796112, 2021). "In addition, we also found that SNCG and CDK6 are related to prognosis of glioma; SNCG to dendritic cells; and CDK6 to immunity." (PMID 34615480, 2021). "In summary, our findings suggested that the expression of H19 was elevated in glioma, which could promote the growth, invasion and migration of tumor cells via H19/miR-200a/CDK6/ZEB1 axis." (PMID 34796112, 2021). "CDK6 is a key regulatory factor in the cell cycle and a cancer-promoting factor in gliomas." (PMID 34615480, 2021). "MicroRNAs (MiRNAs) blocking the expression of CDK6, which can inhibit the proliferation of many solid tumour cells, such as gliomas, medulloblastoma, prostate, bladder, gastric, hepatocellular and lung, suggesting that CDK6 plays an important role in the development of these tumours." (PMID 33586348, 2021). "Taken together, these results demonstrated that HDGF-mediated c-Jun regulation could promote glioma cell proliferation by inducing CCND1/CDK4/CDK6." (PMID 34959221, 2021). "H19-derived miR-675 might regulate glioma-cell proliferation and migration through cyclin dependent kinase 6 (CDK6) and Cadherin 13 (CDH13), and predict poor prognosis for patients with glioma." (PMID 32650527, 2020). "Overexpression of ANXA2 and CDK6 has previously been reported in canine gliomas and CMT cell lines." (PMID 30517191, 2018). "NEAT1 maintains stem-like properties in glioma cells by modulating the miR-107/CDK6 pathway." (PMID 29552296, 2018). "Up-regulation of CDK6 might be correlated with the malignancy of glioma, promoting both its proliferative and invasive capabilities." (PMID 28467792, 2017). "Over-expression of miR-495 in glioma cells downregulates the expression of cyclin-dependent kinase 6 (CDK6) and inhibits retinoblastoma phosphorylation, and knockdown of CDK6 results in cell cycle arrest at the G1/S transition and inhibition of cell proliferation." (PMID 26863629, 2016). "In glioma, CDK6 knockdown was found to increase sensitivity to chemotherapy." (PMID 25889927, 2015). "In contrast, expression of miR-495 (a putative regulator of CDK6 expression) is low in glioma tumor tissues, whereas its over-expression appears to block or delay the G1/S transition of the cell cycle by downregulating CDK6, thus inhibiting proliferation of malignant glioma cells." (PMID 23594394, 2013). "It is worth noting that there may be other biomarkers for response such as amplification of D-type cyclins, CDK4 or CDK6 amplifications- all of which are present in DIPGs and other pediatric high-grade gliomas." (PMID 24098593, 2013). "Cooperating with miR-124, miR-137 may suppress expression of phosphorylated Rb and CDK6 while inducing cell cycle arrest at G0/G1 in glioma cells." (PMID 23358700, 2013). "Furthermore, miR-495 regulated CDK6 expression and involved in glioma cell growth inhibition, which indicated the possible role of miR-495 in tumor progression." (PMID 23594394, 2013). "In fact, two independent studies in glioma, another type of brain tumor, showed an overexpression of circHIPK3 and its involvement in the disease by reducing the expression of miR-421 and miR-124, which prevent cell proliferation and growth through CDK6 inhibition." (PMID 37835380, 2023). "Notably, previous work also highlighted the importance of CDK6 in glioma." (PMID 33589577, 2021).
glioma (continued). "Moreover, LINC00473 can act as a ceRNA on miR-637 to regulate CDK6 expression and have cancer-promoting effects on glioma, whereas lncRNA MATN1-AS1 can have ceRNA-like effects on miR-200b/c/429 to increase CHD1 expression, thereby promoting the progression of glioma." (PMID 34615480, 2021). "Therefore, PCGEM1 regulates miR-539-5p/CDK6 axis to promote glioma progression." (PMID 33589577, 2021). "CDK6 could promote cell proliferation and its expression was remarkably increased in glioma." (PMID 34796112, 2021). "Indeed, a recent study suggests that SNHG15 targets CDK6 in glioma." (PMID 34734088, 2021). "Furthermore, H19 could serve as a miRNA precursor and modulate glioma progression by generating miR-675, which could regulate the proliferation and migration of glioma cells by inhibiting the expression of CDK6." (PMID 31052326, 2019). "Using CDK6 inhibitor, palbociclib could effectively suppress tumorigenic properties in TMZ-R cells and decrease TMZ-R’s ability to generate M2 GAM and glioma stem cells, in association with down-regulation of lncSNHG15 and up-regulation of tumor suppressor miR-627." (PMID 31462285, 2019). "In addition CDK6 activates transcription factor E2F1/2 that might activate several drug-resistant genes which are up-regulated in glioma cells." (PMID 28467792, 2017). "Thus, CDK6 expression correlates with the density of malignant cells in tumor-affected regions, and may be involved in the microenvironments of scattered glioma cells." (PMID 23594394, 2013). "In addition to the miRNA delivery in vitro, we also found that BM-MSCs that were administered ipsilaterally were able to peripherally penetrate the U87-derived xenografts, deliver the Cy3-miR-124 to nearby glioma cells and downregulate the expression of the miR-124 target gene, CDK6." (PMID 23548312, 2013). "Chromosome 7, with frequent copy number gains in all four cancers, harbors several key oncogenes such as EGFR, CDK6, and MET in glioma; KMT2C and PMS2 in medulloblastoma; BRAF, RAC1, and TRRAP in melanoma." (PMID 41537310, 2026). "In glioma and ovarian cancers, NAP1L1, via its interaction with HDGF, activated c-Jun, an oncogenic transcription factor, to induce CCND1/CDK4/CDK6 expression resulting in cellular proliferation and chemoresistance to cisplatin." (PMID 40176914, 2025). "Its predicted target genes include four hub genes, CCND1, SP1, CDK6 and CDK4, which are directly or indirectly involved in glioma development." (PMID 39348350, 2024). "CF-ME induced G1 phase cell cycle arrest in glioma cells, potentially mediated by upregulation of GADD45A and p21 and downregulation of CDK6." (PMID 39408228, 2024). "The results showed that patients in different groups defined by age, FGFR2, IDH1, CDK4, CDK6, KIT, and CDKN2A had significantly different OS in all glioma grades." (PMID 37273702, 2023). "INHEG activation enhances rRNA 2’-O-methylation, thereby increasing the expression of oncogenic proteins including EGFR, IGF1R, CDK6 and PDGFRB in glioma cells." (PMID 37980347, 2023). "Age, FGFR2, IDH1, CDK4, CDK6, KIT, and CDKN2A were considered vital indicators related to the prognosis and OS time of glioma." (PMID 37273702, 2023). "Based on their prognostic relevance in glioma samples, the seven variables age, FGFR2, IDH1, CDK4, CDK6, KIT, and CDKN2A were selected for the construction of the WHO5 risk signature." (PMID 37273702, 2023). "We found that the protein levels of cyclin D1, CDK6 and CDC6 were reduced in UM-164-treated glioma cells in both dose- and time-dependent manners." (PMID 36358761, 2022). "In human glioma, UCA1 knockdown inhibits the proliferation and migration of cells through miR-193a-mediated downregulation of CDK6, and blocks the Notch signaling pathway by decreasing the expression levels of phosphorylated Notch1, Notch2 and Notch3 proteins." (PMID 33777227, 2021).
glioma (continued). "Our study for the first time defined the role of PCGEM1in glioma and illustrated the regulatory relationship between PCGEM1 and miR-539-5p/CDK6 axis." (PMID 33589577, 2021). "Western blot analysis and IHC showed that cyclin D1, cyclin D2, CDK4, CDK6, Ki-67, Bcl-2 and Bax were involved in the NRXN3-induced inhibitory effect on glioma growth." (PMID 34035217, 2021). "In this study, the expression of H19, miR-200a, CDK6 and ZEB1 as well as their interaction in glioma have been investigated." (PMID 34796112, 2021). "Due to heterogeneity of glioma, we additionally investigated the patient prognosis with CDK4/CDK6 and TUBA1C expression in every grade of glioma in CGGA datasets." (PMID 32860670, 2020). "Previous studies have shown that miR186 targeted IGF-1R in glioma, and Yin Yang 1 (YY1) and cyclin dependent kinase 6 (CDK6) in prostate cancer." (PMID 32082999, 2020). "Studies have identified several common genes and miRNAs that are ceRNA partners of NEAT1 different cancer types, for example, the NEAT1/miR-107/CDK6 (cyclin dependent kinase 6) axis is deregulated in laryngeal squamous cell carcinoma (LSCC) and glioma." (PMID 29702599, 2018). "Prior reports have shown that miR-34a is downregulated in GBM compared to normal brain, and that it inhibits cell proliferation, survival, and invasion in adherent glioma cell lines by targeting MET, NOTCH1, NOTCH2, and CDK6." (PMID 22479456, 2012). "Moreover, the concurrent alteration of the FRA1 targets, AXL, CDK6, and FSCN1 correlated with worse prognosis in lung adenocarcinoma, low grade glioma, and clear cell renal cell carcinoma." (PMID 41286309, 2025). "Interestingly, most of these proteins are ECM molecules and contribute to the invasiveness of glioma cells, including FN1, TNC, LAMC1, COL1A1, EGFR, CDK6, and COL6A2." (PMID 37059730, 2023). "Gliomas with BRAF gains commonly had concomitant gains in MET, SMO, EZH2, and CDK6 (p < 0.001 each), along with other genes on 7q, which may reflect larger chromosomal duplications." (PMID 36854806, 2023). "Finally, we combined the results of the XGB model and univariate Cox regression analysis to identify age, FGFR2, IDH1, CDK4, CDK6, KIT, and CDKN2A as crucial predictors of prognosis and OS time for glioma patients." (PMID 37273702, 2023). "SUMO1 is upregulated in glioma cells and tissues, and the SUMO1 modification of the cell cycle regulator CDK6 could upregulate its expression by stabilizing it and, thus, could promote cell malignant progression." (PMID 37906341, 2023). "These miR-637-targeted genes include HMGA1, CDK6, and WNT7A in glioma, HEMGN in PTC, APLN in GC, USP21 in HCC, LY6E and CTSB in CHOL, NUPR1 in OSCC and MM, HDAC4 in SaOS, ABL1 in CML, KLK4 in OC, PLXNB2 in OC, AKT1 in TNBC, PTC, and HCC, AKT3 in TNBC, and RING1 in CCa." (PMID 36175921, 2022). "Furthermore, miR-637 inhibited cancer cell invasion in glioma and HCC by targeting CDK6 and USP21, respectively." (PMID 36175921, 2022). "Similarly, NEAT1 knockdown targets miR-132, which regulates the oncogene sex determining region Y-box protein 2 (SOX2) and miR-107, a modulator of cyclin-dependent kinase 6 (CDK6) and CDK14; these findings were closely connected with glioma malignancy." (PMID 33980320, 2021). "Furthermore, the biological effects of H19, miR-200a, CDK6 and ZEB1 in glioma tissues/cells were also elucidated in vivo and in vitro." (PMID 34796112, 2021). "In summary, NAP1L1 could promote proliferation and chemoresistance in glioma cells by interacting with HDGF and activating c-Jun to induce the expressions of CCND1/CDK4/CDK6." (PMID 34959221, 2021). "Thus, we developed a prognostic prediction model for glioma patients using four mRNAs, namely, SNCG, PGD, CDK6, and GCC1." (PMID 34615480, 2021). "While BTK was overexpressed in 14 hematopoietic tumors, CDK6 was overexpressed in both hematopoietic and nonhematopoietic tumors, including neuroblastoma and glioma." (PMID 31651965, 2019).
glioma (continued). "Chen and co-workers showed that Cyclin-dependent kinase 6 (CDK6), which is a key component in maintaining the G1 to S phase transition, could promote cell proliferation, and its expression was significantly upregulated in glioma tissue samples and cell lines." (PMID 37239035, 2023). "In glioma, miR-34a suppresses cell cycle progression and proliferation of glioma cells through direct inhibition of the expression of MET receptor tyrosine kinases (c-MET RTK), Notch-1, Notch-2, cyclin-dependent kinase 6 (CDK6), cyclin 1 (CCND1), and silent information regulator 1 (SIRT1)." (PMID 35922753, 2022). "Moreover, lncRNA NEAT1 promotes glioma pathogenesis though many of other pathways including NEAT1/miR-449b-5p/c-Met axis, NEAT1/MiR-92b, TLR9/NEAT1/STAT3, NEAT1/microRNA let-7e, miR-152-3p/CCT6A, and miR-139-5p/CDK6." (PMID 33393590, 2021). "Moreover, the novel feedback loop involving H19/miR-200a/CDK6 and ZEB1 could regulate the proliferation, invasion and migration of glioma cells." (PMID 34796112, 2021). "In addition, by using GEPIA web tool, the up-regulation of CDK6 was further confirmed in glioma samples (GBM) compared to noncancerous tissues (Tumor=163, Normal=207, p<0.05)." (PMID 34796112, 2021). "The patients with higher CDK6 expression had shorter survival rates than those of the counterparts in grades III and IV primary glioma and recurrent glioma, but not in stage II." (PMID 32860670, 2020). "As analysed in the same cyclin D3 co-immunoprecipitations in T98G glioma cells, serum stimulates the activating phosphorylation of CDK4 but not that of the related CDK6." (PMID 17092340, 2006). "In T98G glioma cells, serum stimulates the phosphorylation of cyclin D3-bound CDK4 but not cyclin D3-bound CDK6." (PMID 17092340, 2006). "However, the biological effects of H19, miR-200a, CDK6 and ZEB1 as well as their interaction in glioma has not been elucidated." (PMID 34796112, 2021).